DNMT1 (DNA methyltransferase 1)
Diseases named in the same sentence as DNMT1 in open-access papers (continued):
Sharing a sentence is not in itself a finding about the gene and the disease.
breast cancer (continued). "Whilst breast cancer cells treated with 2 mM sodium valproate demonstrated a down-regulation of structural maintenance of chromatin protein 1 (SMC1), DNA methyltransferase 1 (DNMT1) and heterochromatin protein 1 (HP1), proteins known to maintain heterochromatin structures." (PMID 28542253, 2017). "DNA methyltransferase (DNMT) is the key enzyme involved in hypermethylation, including DNMT1, 2, 3A, 3B, and 3L, which were repored to be dysregulated in oral cancer, ovarian cancer, breast carcinoma and lung cancer." (PMID 28938637, 2017). "In agreement, our ChIP assays showed that DNMT1/3a/3b and the transcriptional repressive histone mark H3K27me3 are recruited to the promoter region of FOXO3 in BRCA1-low and -mutated breast cancer cell lines but not in BRCA1-competent MCF-7 cells." (PMID 27043660, 2016). "DNMT1 was highly expressed in TNBC and in breast cancer with inflammatory stromal type." (PMID 27071379, 2016). "It has been shown that DNMT1 stability is regulated by a mechanism involving in acetylation-driven ubiquitination, and HDAC inhibition promotes ubiquitin-dependent degradation of DNMT1 in breast cancer cells." (PMID 27177222, 2016). "Although Spearman’s r was not high, there appears to be a negative correlation of DNMT1 or DNMT3B mRNA expression with RASSF1A expression only in breast cancer." (PMID 27294960, 2016). "They found that depletion of DNMT1 had the strongest effect on colony growth suppression in cellular transformation but did not induce cellular invasion in MCF-7 and ZR-75-1 non-invasive breast cancer cell lines." (PMID 24822169, 2014). "Studies have also shown that disruption of transcriptional repressor multi-molecular complex, HDAC1/DNMT1/SUV39H1, is associated with ERα transcriptional activation in ERα-negative breast cancer cells." (PMID 22662208, 2012). "Panobinostat was shown to downregulate DNMT1 without affecting DNMT3a and 3b in human breast cancer cells and human acute leukemia cells while we observed an additional effect on DNMT3a in the used HCC cell lines." (PMID 22943463, 2012). "DNA methyltransferases (DNMTs), especially DNMT1 and DNMT3a, were also decreased in SFN-treated breast cancer cells suggesting that SFN may repress hTERT by impacting epigenetic pathways." (PMID 20625516, 2010). "Targeting DNMT1 or RASSF1A—through small molecule inhibitors, epigenetic modulators, or gene therapy—may offer more precise and effective treatment options for patients with breast cancer." (PMID 41381440, 2025). "For example, DNMT1 which belongs to the family of DNA methyltransferases not only regulated stemness and tumorigenicity of liver cancer and breast cancer, but also predicted poor prognosis of cervical cancer and breast cancer." (PMID 37120564, 2023). "GSK3B silencing could prevent histone H3 phosphorylation and reduce DNMT1 expression, thereby inhibiting the proliferation of breast cancer cells induced by high glucose, and the expression of GSK3B and DNMT1 proteins are in the same direction in breast cancer cells." (PMID 35747513, 2022). "Accordingly, we first analyzed the expression patterns of miR-497 and DNMT1 in breast cancer and adjacent normal tissues collected by TCGA through the UALCAN database, and found that miR-497 was poorly-expressed and DNMT1 was highly-expressed in breast cancer relative to adjacent normal tissues." (PMID 35255904, 2022).
breast cancer (continued). "At the same time, scientific studies have shown interference in DNA methyltransferase (DNMT) activity, in particular DNMT1 and DNMT3a, which have been reduced in breast cancer cells treated with SFN, suggesting that this compound may be able to repress hTERT through specific epigenetic pathways." (PMID 36235389, 2022). "It was further revealed that lower ISL1 transcript expression was significantly correlated with poorer survival in breast cancer patients (p < 0.05); however, it was not demonstrated whether DNMT1 expression was inversely correlated in breast cancer patients." (PMID 34360879, 2021). "Importantly, we observed a significant inverse correlation between FOXO3a and FOXM1/SOX2/DNMT1 expression levels, and a significant positive correlation between FOXM1, SOX2, and DNMT1 in the breast cancer tissue set, which was consistent with our finding in vitro and in animal model." (PMID 31296961, 2020). "In summary, our findings demonstrate that DNMT1/FOXO3a/FOXM1/SOX2 signaling promotes BCSC properties, which might contribute to tumor initiation and progression in breast cancer, and that targeting this signaling is a potential therapeutic strategy for breast cancer." (PMID 31296961, 2020). "The detailed mechanisms of antitumor function of FBP1 are still remaining to be unclear; it has elucidated that Snail-G9a-Dnmt1 complex is critical for FBP1 silence, which promoted the interaction of β-catenin and TCF and played an important role in EMT transformation in basal-like breast cancer." (PMID 29984231, 2018). "Thus, we demonstrated that the downregulation of CLDN6 is regulated through promoter methylation by DNMT1, which depends on the SMAD2 pathway, and that CLDN6 is a key regulator in the SMAD2/DNMT1/CLDN6 pathway to inhibit EMT, migration and invasion of breast cancer cells." (PMID 28867761, 2017). "Our results identified high tumor expression of DNMT1 in TNBC and low tumor expression of DNMT 1 in luminal A type, concordant with a previous study in which DNMT1 expression was reported to be increased in breast cancer compared to other benign lesions, especially in ER-negative breast cancer." (PMID 27071379, 2016). "In addition to DNMT1, DNMT3A was also found to be elevated in sporadic breast cancer." (PMID 27525019, 2016). "Moreover, a breast cancer study demonstrated that tea polyphenols [catechin, epicatechin, and (−)-epigallocatechin-3-O-gallate (EGCG)] and bioflavonoids (quercetin, fisetin, and myricetin) inhibited DNMT1-mediated DNA methylation in a dose dependent manner." (PMID 24822169, 2014). "However, whether DNMT1 plays a key role in TAM-induced breast cancer progression has not yet been reported." (PMID 36273188, 2022). "Additionally, our findings further revealed iDNMT1 could promote chemotherapy resistance and metastasis of breast cancer cells, as evidenced by decreased IC50 value of ADR, diminished cell invasion and migration along with decreased apoptosis as a result of DNMT1 knockdown." (PMID 35255904, 2022). "In addition, DNMT1 was not inhibited by 5-aza-dc in all three breast cancer cells tested." (PMID 20132554, 2010). "At the TP53BP2 gene promoter in HeLa cells and the RASSF1A gene promoter in MDAMB-231 breast cancer cells, SETDB1 interacts preferentially with the de novo DNA methyltransferase DNMT3A, but not with the maintenance methyltransferase DNMT1." (PMID 38904842, 2024). "At the TP53BP2 gene promoter in HeLa cells and the RASSF1A gene promoter in MDAMB-231 breast cancer cells, SETDB1 interacts with DNMT3A, but not with the maintenance methyltransferase DNMT1." (PMID 38904842, 2024).
breast cancer (continued). "Although GSK-3685032 decreased DNMT1 protein levels, it did not upregulate TROP2 expression in these breast cancer cell lines." (PMID 37567892, 2023). "Tumor growth was impaired when Dnmt1 was disabled in ECs, but not in fibroblasts using Postn-cre mice, with orthotopically engrafted EO771 and PyMT mammary tumor cells." (PMID 37055433, 2023). "OCT4 does not promote the expression of DNMT1 in ERα-positive breast cancers because ERα occupies the ERE sequence in the promoter region of DNMT1 and inhibits DNMT1 expression." (PMID 32365920, 2020). "DNMT1 inhibitor 5-aza-2′-deoxycytidine (AZA) and HDACi trichostatin A (TSA) induces ERα expression in ERα-negative breast cancer cells." (PMID 21814622, 2011).
lung carcinoma (175 papers, 2007 to 2026). "Increased COL1A1 mRNA expression in bronchoalveolar lavage cells from human patients suffering from idiopathic pulmonary fibrosis and lung cancer is presumed to be the consequence of DNMT1 regulation, although the underlying mechanism remains to be elucidated." (PMID 37373151, 2023). "NARFL deficiency caused dysregulation of energy metabolism in lung cancer cells via HIF-1α–DNMT1 axis, which promoted drug resistance and cell migration." (PMID 37821486, 2023). "Overexpression of DNMTs has been frequently observed in lung cancer with upregulation of DNMT1, and is consistently and independently associated with poor prognosis." (PMID 35205708, 2022). "Overexpression of DNMT1 in lung cancer is associated with increased expression of histone deacetylases (HDACs) which increases the stability of DNMT1 and in turn stimulates cancer progression." (PMID 29728663, 2018). "Meanwhile, the expression levels of DNA methyltransferases including DNMT1 is frequently elevated in lung cancers, which is significantly associated with the hypermethylation of the p16 promoter." (PMID 28427182, 2017). "The results in vitro implicated that, similar to the DNMT1 inhibitor 5-Aza-CR, loss-of-function of DNMT1 by siRNA was able to inhibit the growth and migration of lung cancer cells." (PMID 28938637, 2017). "Strong nuclear staining of DNMT1 protein in lung tumor tissues is significantly associated with smoking status of lung cancer patients." (PMID 25949795, 2014). "Moreover, DNMT1 is implicated in the upregulation of the lung cancer stem-like cell (LCSLC) population." (PMID 38622665, 2024). "In the process, they found that the decrease of DNMT1 caused a reduction in the occurrence of lung cancer resulting from tobacco tormogens, and DNMT activity was also suppressed in pneumocytes that could induce lung cancer." (PMID 36091786, 2022). "The antibiotic mithramycin A (MMA) is a potential DNMT1 inhibitor, which could reduce the CpG island methylation of SLIT2 and TIMP-3 genes and could cause the degradation of DNMT1 in lung cancer cells." (PMID 37077808, 2022). "Since PD-L1 overexpression transiently occurs during the cytokine-driven epithelial mesenchymal transition (EMT), a strong link between PD-L1 promoter demethylation and the TGF-β signaling pathway was found, which was associated with the loss of DNA methyltransferase 1 (DNMT1) in lung cancer cells." (PMID 31817953, 2019). "In this study we tested this hypothesis by showing DBCCR1, a potential methylation target in bladder cancers, is decreased in human lung cancers and associated with an elevation of DNMT1." (PMID 28427182, 2017). "It is already known that p21 expression can increase after inhibition of the HDACs in different cancer models, and that the inhibition of DNMT1 and HDACs results in increased p21 expression in lung cancer models." (PMID 40498028, 2025). "In conclusion, this study highlights the critical roles of CIP2A, RING1, and DNMT1 in the development and progression of lung cancer." (PMID 41362702, 2025). "This suggests that SM down‐regulates ERK1/2 phosphorylation by inhibiting EP4 protein expression, decreasing DNMT1 and c‐Jun protein expressions to inhibits the growth of lung cancer cells." (PMID 39155844, 2024).
lung carcinoma (continued). "HPV oncoprotein E7 interacts with the DNA methyltransferase DNMT1, an overregulated common gene in lung cancer, stimulating its methyltransferase activity to induce epigenetic reprogramming in tumor cells." (PMID 39228892, 2024). "This study aimed to elucidate the underlying mechanism involving the DNMT1/miR-152-3p/SOS1 axis in regulating the self-renewal and tumor growth of LCSLCs (lung cancer stem-like cells)." (PMID 38622665, 2024). "Our analysis of collected lung cancer specimens revealed elevated expression levels of DNMT1, CD44, and SOS1 in certain NSCLC tissues, establishing a positive correlation between DNMT1 and SOS1 in the progression of NSCLC." (PMID 38622665, 2024). "We have also shown that dual G9a/DNMT1 blockade plays an antitumor and antimetastatic effect in NSCLC models and that the G9a/DNMT1-targteting drug CM-272 acts as a lung cancer drug sensitizer." (PMID 39488528, 2024). "For example, DNA methyltransferase 1 (DNMT1), a key enzyme in DNA methylation, is associated with resistance to cisplatin in several cancers, including non–small cell lung cancer (NSCLC), lung cancer, and ovarian cancer." (PMID 39487556, 2024). "Metformin dose-dependently downregulated expression of DNMT1 and DNMT3a at the post-transcriptional level and expression of DNMT3b at the transcriptional level in A549 lung cancer cells." (PMID 36959680, 2023). "In summary, our study reveals that long-term gefitinib/osimertinib exposure enhances genome-wide methylation and promotes drug resistance in lung cancer cells through UHRF1/DNMT1-mediated epigenetic silencing of MUC17." (PMID 36778111, 2023). "In lung cancers, DNMT1 overexpression led to the hypermethylation and dysregulation of multiple tumor suppressor genes, including p16, RARβ, FHIT, and RASSF1A." (PMID 36979633, 2023). "Altered expression levels of DNMT1, DNMT3a, and DNMT3b proteins have been found in patients with lung cancers, especially in smokers, and are correlated with hypermethylation of tumor suppressor genes." (PMID 36959680, 2023). "DNMT1 is highly expressed in a variety of tumors including lung cancer, leukemia, gastric cancer, and liver cancer, and the expression of DNMT1 in pancreatic cancer tumor tissue is significantly correlated with the degree of tumor malignancy." (PMID 37876534, 2023). "DNMT1 overexpression was found in pituitary adenoma, pancreatic cancers, gastric cancers, lung cancers, and thyroid cancers." (PMID 36979633, 2023). "Another lncRNA, NEAT1, interacts with DNMT1, orchestrating cytotoxic T cell infiltration in lung cancer." (PMID 37880732, 2023). "Gallic acid (GA) alters methylation of lung cancer and pre-malignant oral cell lines, and significantly suppresses cytoplasmic and nuclear DNMT1 and DNMT3B within 1 week." (PMID 36232871, 2022). "It is well-documented that DNMT1 is an oncoprotein in both solid and hematological malignancies, and DNMT1 has been reported to exert oncogenic effects in multiple cancers, such as BC, lung cancer, colon cancer, and osteosarcoma." (PMID 36091786, 2022).